CXCR2 (C-X-C motif chemokine receptor 2)
Diseases named in the same sentence as CXCR2 in open-access papers (continued):
Sharing a sentence is not in itself a finding about the gene and the disease.
glioma (continued). "The CXCR2/CXCL2 signaling represents a promising therapeutic target in glioma." (PMID 37012233, 2023). "In addition, CXCR2 antagonization (SB225002) inhibits glioma growth during tumor initiation and progression and presents a significantly decreased infiltration of TAM in recurrent tumors." (PMID 37012233, 2023). "Circ-0000215 and CXCR2 expression were significantly increased in glioma cells and tissues." (PMID 35883576, 2022). "In this study, CCL2, CCL5, CXCR4, MMP9, and CXCR2 expression was found to be high in TERTmut glioma from all samples and IDHwt subgroups with high levels of neutrophil infiltration, which indicated that N2 phenotype neutrophils were associated with TERT mutation." (PMID 33996815, 2021). "In addition, blocking of this signaling by anti-CXCR2 antibody or by CXCR2 inhibitor resulted in suppressed glioma growth and cell migration." (PMID 32456359, 2020). "However, new clinical studies will need to be performed to test the clinical feasibility of using GSVA for preventative and personalized medicine approaches in studies on glioma, subtypes of liver cancer and for response to dual CXCR2/CCR5 therapy." (PMID 31039157, 2019). "Increased CXCL1 expression was closely related to immunosuppressive characteristics in gliomas, possibly via remodeling the TIME composition by recruiting CXCR2+ inflammatory immune cells." (PMID 38342629, 2024). "By targeting the miR-495-3p/CXCR2/PI3K/Akt axis, overexpression of circ-0000215 can increase glioma growth." (PMID 35883576, 2022). "Among them, one gene (CXCR5) was downregulated while five other genes (CXCR1, CXCR2, CXCR3, CXCR4, and ACKR3) were enriched in glioma compared with normal brain tissues." (PMID 35571062, 2022). "The alternative proangiogenic factors CXCL2 and IL8, which act through CXCR2 or CXCR1, seem to be promising therapeutic targets due to their expression in glioma cell lines and mouse models." (PMID 33807899, 2021). "In their U87 glioma mouse model, CAR T cells with both CXCR1 and CXCR2 showed enhanced migration to the tumor and decreased tumor growth compared to the control groups." (PMID 34203660, 2021). "In TCGA database, GBM tissue had higher CXCR1, CXCR2, CXCR4, and CCR5 expression compared with WHO grade II and III glioma." (PMID 34638384, 2021). "We found that the following neutrophil chemokines—MMP9, CCL2, CCL5, CXCR4, CXCR2, CCL23, and IL8 (p = 0.07)—were enriched in TERTmut gliomas (t-test, p < 0.05)." (PMID 33996815, 2021). "The authors found that IL-8/CXCR2 signaling supports the self-renewing capacity of GBM cells and increased the expression of glioma-initiating cell markers." (PMID 34203660, 2021). "Co-expression of the IL-8 receptor, CXCR1/CXCR2, was found to enhance CAR-T cells trafficking and persistence in the tumor in a glioma mouse model." (PMID 33154756, 2020). "Additionally, both IL8 and CXCL2 upregulation was observed in vitro after exposing glioma cells to TMZ, which suggests a potential role of the CXCR2 signaling pathway in the development of resistance against TMZ." (PMID 34681839, 2021). "While CXCL2, IL8 and their respective receptor CXCR2 seem to contribute to angiogenesis and tumorigenesis in GBM, there is also evidence suggesting an important role of those molecules in circumvention of anti-angiogenic therapy in gliomas." (PMID 33807899, 2021). "CXCL2 is another ligand of CXCR2 and, in recent reports, the axes CXCL2-CXCL8/CXCR2 is described as an important signaling pathway modulating GBM angiogenesis, alternative to the well-known VEGF-VEGFR one, thus representing a new target for glioma therapy." (PMID 33066172, 2020). "In addition, a previous report demonstrated that migration of UCB-MSC towards glioma cells was higher when compared to BM-MSCs likely due to increased levels of the IL-8 receptor, CXCR1, and CXCR2 in the former cell type." (PMID 25147818, 2014). "Contrary to our results they did not observe any expression of CXCR2 in gliomas." (PMID 30086759, 2018).
chronic obstructive pulmonary disease (27 papers, 2011 to 2025). A chronic and progressive lung disorder characterized by the loss of elasticity of the bronchial tree and the air sacs, destruction of the air sacs wall, thickening of the bronchial wall, and mucous accumulation in the bronchial tree. "In particular, a CXCR2 antagonist may be useful in the treatment of respiratory diseases such as chronic obstructive pulmonary disease (COPD) that are associated with a high tissue burden of activated neutrophils." (PMID 26092545, 2015). "One clinical trial (NCT03250689) examined the effect of Danirixin, a selective CXCR2 antagonist, on NETs in chronic obstructive pulmonary disease (COPD) patients." (PMID 34204306, 2021). "In patients with chronic obstructive pulmonary disease, CXCR2 antagonist decreases absolute neutrophil counts, reduces biological inflammation and disease symptoms." (PMID 30304046, 2018). "The association of CXCR2 with NET formation has been documented, as demonstrated by a significant reduction in NET formation in neutrophils from individuals with chronic obstructive pulmonary disease (COPD) following treatment with a selective CXCR2 antagonist." (PMID 38308301, 2024). "Low molecular weight IL-8/CXCR2 antagonists have been tested in clinical trials for asthma, chronic obstructive pulmonary disease (COPD) and influenza, and have shown suppression of pulmonary neutrophilia and a decrease in the signs of NETosis, but they have not been tested in COVID-19 trials." (PMID 33584318, 2021). "Furthermore, Danirixin (GSK1325756), a selective CXCR2 antagonist, has been found to alleviate the symptoms of patients with chronic obstructive pulmonary disease (COPD) by inhibiting the formation of NETs (NCT03250689)." (PMID 34868992, 2021). "CXCR2 is obviously upregulated in airway epithelial cells during acute exacerbations of chronic obstructive pulmonary disease (COPD), and there is a significant positive correlation between CXCR2 expression and the number of neutrophils." (PMID 35702353, 2022). "In patients with chronic obstructive pulmonary disease (COPD), clinical trials are ongoing with CXCR2 inhibitors to reduce NET formation and improve lung function." (PMID 35158948, 2022). "Cxcr2, a CXC chemokine receptor, is commonly overexpressed in pulmonary diseases such as acute lung disease, chronic obstructive pulmonary disease, and new BPD." (PMID 36976210, 2023). "CXCR2 is particularly involved in neutrophil recruitment, tumor progression, and the establishment of a pre-metastatic niche, which makes it a popular target for diseases such as chronic obstructive pulmonary disease (COPD), rheumatoid arthritis, asthma, and cancer." (PMID 40727104, 2025). "Therefore, the CXCL8/CXCR2 axis antagonists have been evaluated in clinical trials of various respiratory distress conditions in influenza, eczema, and chronic obstructive pulmonary disease (COPD)." (PMID 36187170, 2022). "CXCR2 has become a therapeutic target for many inflammatory diseases, such as chronic obstructive pulmonary disease (COPD), allergic asthma, gram-negative sepsis, IBD, lung injury, auto-immune diseases and cancer." (PMID 38034382, 2023).
influenza (22 papers, 2011 to 2024). An acute viral infection of the respiratory tract, occurring in isolated cases, in epidemics, or in pandemics; it is caused by serologically different strains of viruses (influenzaviruses) designated A, B, and C, has a 3-day incubation period, and usually lasts for 3 to 10 days. "CXCR2-deficient mice had less lung injury and lethality after a challenge with influenza-specific CD8+ T cells." (PMID 29326698, 2017). "The observed high expression of these surface markers indicated that a reduced CXCR2 signaling caused pulmonary macrophages surrounded by an innate immune microenvironment induced by influenza infection to convert into M2-like macrophages that possibly produced CXCL13." (PMID 34868067, 2021). "A number of studies on the experimental inhibition of CXCR2 have reported its ameliorative effects on inflammatory responses and lung injury in the sublethal influenza murine models." (PMID 37957672, 2023). "In mouse models of influenza, CXCR2 is required for homing of neutrophils to the lung, and treatment with a CXCR2 inhibitor reduced lung pathology." (PMID 36622345, 2023). "The findings demonstrated that the mRNA levels of CCR5, CCR2, CCR1 and CXCR2 genes were increased after influenza infection." (PMID 37957672, 2023). "Danirixin, another oral selective CXCR2 antagonist, has been investigated in patients with virus infection disease (influenza), which had small-sample clinical trial (NCT02469298)." (PMID 34025668, 2021). "Mice were infected with influenza and treated with a CXCR2 antagonist in combination with antiviral or antiviral alone starting 4 days postinfection." (PMID 31041337, 2019). "In this study, we explored the ability of the CXCR2 antagonist SB-332235Z to reduce excessive neutrophil accumulation and subsequent inflammatory damage in the lungs of influenza-infected mice." (PMID 31041337, 2019). "This study helped enable clinical studies to evaluate the effect of CXCR2 antagonism in subjects with influenza." (PMID 31041337, 2019). "The ameliorative effect of phillyrin on influenza-induced pulmonary pathological damage may be partly related to the antagonization of CXCR2 and inhibition of NLRP3 inflammasome activation." (PMID 37957672, 2023). "Therefore, it is likely that activated CXCR2 signaling restricts CXCL13 expression in influenza-infected AMs via the intracellular pathway, especially the PI3K/AKT cascade." (PMID 34868067, 2021). "Similarly, CCL2 (Ccl2), a ligand for CCR2 that recruits CCR2+ inflammatory monocytes, as well as CXCL1 (Cxcl1), CXCL2 (Cxcl2), and CXCL5 (Cxcl5), which are ligands of CXCR2 that induce neutrophil infiltration in influenza-infected lungs, showed notable decreases in NOD.SCID mice." (PMID 37904257, 2023). "Considering abundant expression of CXCL5 in the infected lung during early influenza infection stage, CXCL5 deficiency might down-regulate CXCR2 axis in lung epithelial cells and lead to reduced CXCL1/2 expression form the cells which in turn decreasing neutrophil infiltration." (PMID 34868067, 2021). "For example, researchers investigated the optimal timing of treatment with a CXCR2 antagonist, SCH527123, and its effectiveness in combination with the antiviral agent, oseltamivir, in mice and piglet influenza-pneumonia models." (PMID 38144312, 2023). "Other similar studies noted reduced neutrophilia with the use of danirixin (a CXCR2 inhibitor) and navarixin (MK-7123/SCH 527123) in phase 2 clinical trials in influenza and COPD cases." (PMID 36187170, 2022). "Neutrophils isolated from influenza-infected mouse lungs were stimulated with CCR1, CCR5, CXCR2, and CXCR3 specific ligands CCL3, CCL4, IL-8, and CXCL11 (100 ng/mL), respectively, and incubated for 4 h." (PMID 31041196, 2019). "It has been previously reported that blocking expression of CXCR2, the receptor for CXCL1, resulted in a reduction of neutrophil influx with prolonged host survival during influenza infection." (PMID 22072963, 2011).
influenza (continued). "Because CXCR2 is a key receptor in the chemotaxis of neutrophils to areas of inflammation, DNX is also in development for uncomplicated influenza and for intravenous (IV) therapy for patients hospitalized with influenza." (PMID 38094741, 2023). "In contrast, the expression of CXCL13 increased markedly in the group treated with CXCL5 and CXCR2 antagonists compared to the group without the CXCR2 antagonist upon influenza challenge." (PMID 34868067, 2021). "Similarly, the CXCR2 inhibitor Danirixin (GlaxoSmithKline) has been tested in phase 2 clinical trials in patients with COPD and influenza, where it reduced neutrophilia." (PMID 32581816, 2020). "Neutrophils isolated from influenza-infected mouse lungs were stimulated with CCR1, CCR5, CXCR2, and CXCR3 specific ligands including CCL3, CCL4, IL-8, and CXCL11 (100 ng/mL) for 20 min, followed by incubation with a 1:10 ratio of Streptococcus pneumoniae (serotype 3) for 90 min." (PMID 31041196, 2019). "The safety results of this study enabled progression of DNX development into hospitalized patients with influenza treated with intravenous DNX and may inform on future studies with this CXCR2 antagonist." (PMID 31024969, 2019). "We confirmed the importance of CXCL2 expression in acute lung injury by transferring influenza-specific CD8+ T cells into transgenic mice lacking CXCR2." (PMID 24223177, 2013). "Indeed, blocking CXCR2 has shown to reduce acute lung injury and inflammation in influenza-infected mice and mice lacking CXCR2 gene have shown decreased inflammation, without affecting viral clearance indicating pathogenic role of neutrophils in severe influenza." (PMID 31041196, 2019). "Both Ly6Chi and Ly6Cint monocytes obtained from the lung of WT and Ifnar1−/− mice expressed CCR2 but not CXCR2, suggesting the critical role of MCP-1 for monocyte recruitment into influenza-infected lung." (PMID 21383977, 2011). "Other studies in mice lacking CXCR2 or CCR2, the primary receptor of CCL2, have shown that blockade of chemokine signaling reduces pulmonary recruitment and subsequently reduces injury and improves survival following influenza infection." (PMID 24223177, 2013).
pancreatic ductal adenocarcinoma (22 papers, 2017 to 2025). An infiltrating adenocarcinoma that arises from the epithelial cells of the pancreas. "Prompted by these promising results obtained in preclinical models, phase I and II clinical trials are evaluating the targeting of CXCR1 and CXCR2 in combination with anti-PD-1 in patients with metastatic melanoma, pancreatic ductal carcinoma, and Ras-mutated MSS metastatic colon carcinoma." (PMID 35158948, 2022). "ATM and WEE1 (DNA damage cell-cycle checkpoint protein) inhibition has been shown to decrease CXCR2 expression and surface PDL1 exposure in human pancreatic ductal adenocarcinoma (PDAC) cells with KRAS mutations." (PMID 38473997, 2024). "One study shows that CXCR2 gene knockout in mice leads to increased liver metastasis arising from pancreatic ductal adenocarcinoma." (PMID 37408240, 2023). "In an orthotopic mouse model of pancreatic ductal adenocarcinoma (PDAC), genetic deletion of CXCR2 in the host resulted in enhanced liver metastasis associated with the expansion of neutrophils and immature myeloid precursor cells." (PMID 35158948, 2022). "In mouse models of pancreatic ductal carcinoma, CXCR2 inhibition resulted in reduced metastases and improved survival." (PMID 35879507, 2022). "Cxcr2 antagonists not only to reduce metastasis, tumor growth and improve response to chemotherapy in the xenograft model, but suppress inflammation-driven intestinal adenocarcinomas and improve survival in a KRas-driven pancreatic ductal adenocarcinoma model." (PMID 29487713, 2018). "Thus, CXCR2 is considered a marker for poor prognosis in many tumor types and, in fact, CXCR2 blockade has been reported to re-educate TAMs and inhibit tumor growth in mouse models of pancreatic ductal adenocarcinoma (PDAC)." (PMID 35053602, 2022). "In the study of pancreatic ductal adenocarcinoma (PDAC), TNF promoted apoptosis of tumour cells by activating the CXCR2-MAPK-TNF signalling cascade response." (PMID 40016789, 2025). "In pancreatic ductal adenocarcinoma (PDAC), TNF promotes tumour cell apoptosis by activating the CXCR2-MAPK-TNF signalling cascade response." (PMID 40016789, 2025). "Through activation of the receptor CXCR2, CXCL1 increases pancreatic ductal adenocarcinoma proliferation." (PMID 37408240, 2023).
renal cell carcinoma (20 papers, 2010 to 2024). "In a renal cell carcinoma in vitro study, primary NK cells were retrovirally transduced with CXCR2, resulting in enhanced migration to the tumor sites." (PMID 39339180, 2024). "A previous study indicated that AKI induces malignant renal cell carcinoma via CXCR2 in the proximal tubular kidney epithelial cells of mice." (PMID 37293297, 2023). "While CXCL5 and/or CXCR2 are increased in patients with renal cell carcinoma, type-2 diabetic nephropathy, or acute rejection of kidney allograft, the role of CXCL5 in mediating continually declining kidney function is not clear." (PMID 35723372, 2022). "Furthermore, CXCR2-transduced NK cells have demonstrated increased migration along CXCR2 ligands or renal cell carcinoma tumor supernatants." (PMID 39134804, 2024). "Various solid tumors, including renal cell carcinoma (RCC), readily secrete ligands for the chemokine receptor CXCR2." (PMID 28923105, 2017). "High expression levels of CXCR2 and CXCR3 in cancer tissues correlated with tumour progression of renal cell carcinoma." (PMID 27297979, 2016). "While human TNBC and renal cell carcinoma (RCC) cells express high levels of CXCR2 ligands including CXCL1 and CXCL2, a lack of CXCR2 expression by activated NK cells can limit their migration towards these tumors." (PMID 38022679, 2023).